MYZAP (myocardial zonula adherens protein)
Description:
Plays a role in cellular signaling via Rho-related GTP-binding proteins and subsequent activation of transcription factor SRF (By similarity). Targets TJP1 to cell junctions. In cortical neurons, may play a role in glutaminergic signal transduction through interaction with the NMDA receptor subunit GRIN1 (By similarity).
Synonyms: Gup; MYOZAP; Gup1; GCOM1; CMD2K
Tractability: Antibody: UniProt places it where antibodies can reach, with medium confidence; UniProt predicts a signal peptide or a membrane-spanning region; its Gene Ontology location is reachable by antibodies, with medium confidence. PROTAC: ubiquitination databases record sites on it.
Gene: Protein-coding gene on chromosome 15 (57,591,900 to 57,685,364, forward strand). Ensembl gene ENSG00000263155.
Subcellular location: Cytoplasm, cytoskeleton; Cell membrane; Cytoplasm, myofibril, sarcomere, I band; Cytoplasm, myofibril, sarcomere, Z line; Cell junction
Gene Ontology:
Molecular function: protein binding
Biological process: intracellular signal transduction
Cellular component: cortical actin cytoskeleton; cytoplasmic side of plasma membrane; I band; plasma membrane; RNA polymerase II, core complex; anchoring junction; cytoskeleton; Z disc
Genetic constraint (gnomAD): Loss-of-function variants: 63 observed, 69.77 expected, observed/expected ratio (o/e) 0.9, 90% interval 0.74 to 1.11. The synonymous counts are far from expectation, so gnomAD's model fits this gene poorly and the ratio says little. Missense variants: 606 observed, 558.13 expected, observed/expected ratio (o/e) 1.09, 90% interval 1.01 to 1.16. Synonymous variants: 254 observed, 203.94 expected, observed/expected ratio (o/e) 1.25, 90% interval 1.12 to 1.38.
Gene-disease validity (ClinGen):
ClinGen rates the evidence that MYZAP causes each of these diseases.
cardiomyopathy, dilated, 2K (autosomal recessive): Moderate.
Homologues: Orthologues: chimpanzee POLR2M (95% identical), macaque MYZAP (94% identical), pig MYZAP (94% identical), rabbit MYZAP (93% identical), rat Myzap (91% identical), mouse Myzap (90% identical), dog MYZAP (88% identical), guinea pig MYZAP (85% identical), tropical clawed frog myzap (55% identical), zebrafish myzap (39% identical). Paralogues in human: TUFT1 (22% identical), CCDC68 (18% identical), POLR2M (11% identical).
Diseases named in the same sentence as MYZAP in open-access papers:
MYZAP is named in the same sentence as 12 diseases in open-access papers, as found by Europe PMC text mining. Sharing a sentence is not in itself a finding about the gene and the disease. The quoted sentences say what the papers report.
atrial fibrillation (3 papers, 2018 to 2023). A disorder characterized by an electrocardiographic finding of a supraventricular arrhythmia characterized by the replacement of consistent P waves by rapid oscillations or fibrillatory waves that vary in size, shape and timing and are accompanied by an irregular ventricular response. "The association of a missense variant in MYZAP with atrial fibrillation and SSS emphasizes the role of the intercalated discs in maintaining normal cardiac rhythm." (PMID 30271950, 2018). "Like p.Gln254Pro in MYZAP, the three low-frequency missense and frameshift variants we have previously reported to increase the risk of atrial fibrillation, in MYH6, MYL4, and PLEC, also increase the risk of SSS8." (PMID 30271950, 2018). "They identify a significant association with coding variants in RPL3L, the first ribosomal gene implicated in atrial fibrillation, and MYZAP, an intercalated disc gene." (PMID 30271950, 2018). "In summary, we report the association of three low-frequency coding variants in RPL3L and MYZAP with increased risk of atrial fibrillation." (PMID 30271950, 2018). "Joint analysis of all data sets yielded genome-wide significant association with atrial fibrillation of all three variants, RPL3L Ala75Val (OR: 1.20, P = 1.7 × 10−14), RPL3L c.1167+1G>A (OR: 1.50, P = 5.0 × 10−10), and MYZAP p.Gln254Pro (OR: 1.38, P = 3.3 × 10−10)." (PMID 30271950, 2018). "No other coding variant in MYZAP associates independently with atrial fibrillation." (PMID 30271950, 2018). "When testing for association with ECG traits using all ECGs irrespective of rhythm and history of atrial fibrillation, p.Ala75Val in RPL3L associates more significantly with ECG measurements and p.Gln254Pro in MYZAP associates with various P wave indices, R amplitude, and T wave indices." (PMID 30271950, 2018).
cardiomyopathies (3 papers, 2018 to 2024). "Overexpression of Myozap, which is a protein encoded by MYZAP, caused cardiomyopathy with hypertrophy and LV enlargement in mice, and exercise accelerated these changes." (PMID 34899865, 2021). "MYZAP, one of the components in GRINL1A CTU, has been linked to cardiomyopathy in zebrafish and mice." (PMID 34899865, 2021). "Cardiomyopathy was not more prevalent in carriers of heterozygous MYZAP LoF variants (2/26; 7.7%) compared with individuals without MYZAP variants (1420/15 552; 8.4%; χ2 test: odds ratio, 0.91 [95% CI, 0.15–3.14])." (PMID 38436102, 2024). "GCOM1/MYZAP variants have not been published as a cause of human cardiomyopathy, but at least one variant has been reported in association with atrial arrhythmias." (PMID 34899865, 2021). "Furthermore, none of 1446 patients with cardiomyopathies studied by whole genome sequencing in the 100 000 Genomes Project England had biallelic LoF variants in MYZAP." (PMID 38436102, 2024). "Similarly, since mutations in intercalated disc genes, albeit not MYZAP, have been associated with cardiomyopathies in man14 we assessed the link between the MYZAP variant and cardiomyopathies in our database, but found none." (PMID 30271950, 2018).
breast carcinoma (1 paper, 2021). "IL21R, IFI30, PI15, and FAM189A2 may be involved in recurrence of Her2-subtype breast cancer IFI30, PI15, FAM189A2, and MYZAP can be used as the specific prognostic markers for Her2-subtype breast cancer." (PMID 33644115, 2021). "These analysis data show that FAM189A2 and MYZAP may be potential prognostic factors in Her2-subtype breast cancer, and their main roles are required to further study." (PMID 33644115, 2021). "In the selected key specific DEGs for Her2-subtype breast cancer, the expression of IL21R, IFI30, PI15, FAM189A2, and MYZAP were significantly correlated with the prognostic survival of the patients." (PMID 33644115, 2021). "In brief, the data in Her2-subtype breast cancer suggest that IL21R, IFI30, and MYZAP may be involved in the tumorigenesis to improve OS of patients with Her2-subtype breast cancer." (PMID 33644115, 2021). "Our analysis showed that FAM189A2 and MYZAP were specifically downregulated in the Her2 subtype, and high FAM189A2 expression predicted high RFS in Her2-subtype breast cancer (p < 0.05), while low MYZAP expression predicted high OS in Her2-subtype breast cancer (p < 0.05)." (PMID 33644115, 2021).
diabetes (1 paper, 2025). "Presently, however, no other literature exists regarding the remaining four critically differentially expressed genes, GRASP, MYZAP, PRKG1, and SMIM24, in diabetes patients." (PMID 40476695, 2025). "Several genes, including GRASP, KRT8, MYZAP, PRKG1, and SMIM24 were differentially expressed in the COVID versus no COVID and diabetes versus no diabetes subgroup analyses." (PMID 40476695, 2025).
cancer (1 paper, 2024). A tumor composed of atypical neoplastic, often pleomorphic cells that invade other tissues. "In addition to detection in cardiac myocytes and endothelial cells, the presence of MYZAP has been demonstrated in adherens junctions in various epithelia, including cancer cells." (PMID 39202370, 2024).
cardiac disease (1 paper, 2024). "Based on our findings, we propose MYZAP as a gene to be considered for evaluation in patients with DCM, particularly among gene-elusive patients with arrhythmogenic DCM whose parents do not show cardiac disease." (PMID 38436102, 2024).
MYZAP also shares sentences with these, for which no sentence is quoted: Alzheimer disease (1 paper); dilated cardiomyopathy (1); Obesity (1); pemphigus (1); Recessive Dilated Cardiomyopathy (1); sick sinus syndrome (1).